GSTP1 (glutathione S-transferase pi 1)
Diseases named in the same sentence as GSTP1 in open-access papers (continued):
Sharing a sentence is not in itself a finding about the gene and the disease.
lung cancer (65 papers, 2007 to 2025). A malignant neoplasm involving the lung. "Santric found a significant association between GSTP1 Ile105Val polymorphism and toxicity. showed that the Kudhair GSTP1 Ile105Val substitution increases lung cancer risk in Arab population." (PMID 39754630, 2025). "The silencing of GSTP1 through promoter hypermethylation has been implicated in the pathogenesis of various cancers, including prostate, breast, and lung cancers." (PMID 40051701, 2025). "African-Americans carrying at least one G allele at the GSTP1 locus were 2.9-fold more likely to have lung cancer (95% CI 1.29-6.20)." (PMID 40958859, 2025). "The variants of the GSTP1 have been associated with susceptibility to various diseases, including colon and lung cancer." (PMID 37886736, 2023). "The underlying mechanism of GSTP1 in the induction of ferroptosis in lung cancer radiotherapy has been proposed in a hypothetical pathway map." (PMID 36589232, 2022). "Otherwise, in 97 patients with advanced non‐small cell lung cancer with the variant alleles at GSTP1 c.313A>G, have notably lower risk of anemia." (PMID 33326171, 2021). "It was assumed that polymorphisms that change the activity of GSTP1 would be risk modifiers and markers in the development of lung cancer." (PMID 32648197, 2021). "The rs1695 SNP in GSTP1, implicated in phase II metabolism of many substrates, including xenobiotics, is recognized as a risk factor for lung cancer." (PMID 32648197, 2021). "Kudhair analyzed Arab populations and revealed that carrying GSTP1 Ile105Val substitution is positively correlated with a higher risk for lung cancer in WP tobacco smokers." (PMID 33280607, 2020). "Genotype combination of GSTM1 (null)/GSTT1 (null) and GSTT1 (null)/GSTP1 (Ile/Ile) considered to be ‘at risk’ genotypes showed strong association towards risk of lung cancer in north Indian population." (PMID 31554367, 2019). "The genotype combination of GSTM1 (null)/GSTT1 (null) and GSTT1 (null)/GSTP1 (Ile/Ile) showed increased susceptibility towards lung cancer." (PMID 31554367, 2019). "The genotype combination of GSTT1 (null)/GSTP1 (Ile/Ile) (p=0.009) was associated with increased lung cancer risk." (PMID 31554367, 2019). "The genotype combination of null GSTT1 and GSTP1 Ile/Ile genotypes (p=0.0001) have two times increased risk of having lung cancer similar to our study." (PMID 31554367, 2019). "Gene set enrichment analysis (GSEA) was performed to evaluate signaling pathways that were associated with Gstp1 expression in the TCGA lung cancer samples." (PMID 31263672, 2019). "The results indicated that the GSTP1 rs1138272 polymorphism appears to be associated with an increased risk of cancer, particularly lung cancer in the Asian population." (PMID 30740061, 2018). "A series of studies demonstrated that the GSTP1 codon 105 polymorphism is associated with various types of cancer, including breast, prostate, and lung cancer." (PMID 23144854, 2012). "We evaluated the impact of polymorphisms detected in 4 in Phase I and Phase II metabolism genes (CYP1A1 MspI T6235C, GSTM1 present/null, GSTT1 present/null and GSTP1 Ile105Val) on the risk of developing lung cancer." (PMID 23013535, 2012). "Some studies have suggested the existence of differences by ethnicity, age of diagnosis, smoking status, and gender in the effect of the GSTP1 polymorphisms on the risk of lung cancer, but evidence is far from enough to draw any conclusions." (PMID 24212786, 2011). "Thirty-five previous meta-analyses have been reported on the individual glutathione S-transferase M1 (GSTM1) present/null, glutathione S-transferase T1 (GSTT1) present/null, and glutathione S-transferase P1 (GSTP1) IIe105Val polymorphisms with lung cancer (LC) risk." (PMID 34190143, 2021). "We have also explored GSTP1 genotypes distribution in cases and controls whether there is more susceptibility towards lung cancer risk of other alleles and genotypes." (PMID 31554367, 2019).
lung cancer (continued). "GSTM1 or GSTT1 gene polymorphism and amino acid changes in GSTP1 have been correlated and may be associated to lung cancer risk." (PMID 31554367, 2019). "Studies investigating the effects of GSTP1 gene polymorphism found that subjects homozygous for the GSTP1 G allele have lower functional levels of the enzyme, and thus are at increased risk for oxidative stress, lung cancer, and asthma." (PMID 25487561, 2014). "This meta-analysis suggests that the GSTP1 341C>T polymorphism may contribute to genetic susceptibility to cancer, especially to lung cancer, and in Asian population." (PMID 23437223, 2013). "Our meta-analysis provide evidence that the variant GSTP1 341C>T may enhance individual susceptibility to lung cancer when special cancer was concerted." (PMID 23437223, 2013). "We investigated if the individual and/or combined modifying effects of the CYP1A1 MspI T6235C, GSTM1 present/null, GSTT1 present/null and GSTP1 Ile105Val polymorphisms are related to the risk of developing lung cancer in relation to tobacco consumption and occupation in Asturias, Northern Spain." (PMID 23013535, 2012). "Among five GSTP1 polymorphisms examined in this study, four polymorphisms (rs749174, rs1871042, rs4891, and rs947895) have been investigated in only a few studies in the context of lung cancer and asthma, and to date, their associations with GC risk have not been determined." (PMID 33634021, 2020). "In addition, the CT genotype of the GSTP1 rs1138272 polymorphism may be linked to the risk of lung cancer in Caucasians." (PMID 30740061, 2018). "The silencing of GSTP1 via promoter hypermethylation is a well-documented epigenetic alteration in several cancers, such as prostate, breast, and lung cancer." (PMID 40051701, 2025). "This study unveils the role of calcium/calmodulin‐‐depdendent protein kinase 2 isoform A (CaMK2A)/nuclear factor erythroid 2‐related factor (NRF2)/glutathione S‐transferase pi (GSTP1) axis under hypoxia in lung cancer stem cell maintenance." (PMID 36709476, 2023). "We also studied the correlation between CaMK2A/NRF2 expression and GSTP1 expression in a lung cancer cell line panel." (PMID 36709476, 2023). "We observed amongst 15 GST isoenzymes, GSTP1 was the only upregulated entity in clinical lung cancers that correlated with adverse patient outcomes." (PMID 36709476, 2023). "Glutathione S‐transferase pi (GSTP1), a phase II detoxification enzyme, is known to be overexpressed and mediates chemotherapeutic resistance in lung cancer." (PMID 36709476, 2023). "Analysis of 15 GST isoforms of human lung cancer using the TCGA dataset showed GSTP1, GSTA2, GSTA5, GSTO2, and GSTZ1 were significantly upregulated in LUAD compared to corresponding normal tissues, suggesting their potential oncogenic effects on LUAD." (PMID 36709476, 2023). "Glutathione S-transferase pi (GSTP1) is a phase II detoxification enzyme that is highly expressed in lung cancer and mediates chemotherapy resistance." (PMID 37941550, 2023). "The first example utilizes handedness and eye-dominance data from 54 studies, the second one employs Type 2 diabetes mellitus and gestational diabetes data from 20 studies, and the third uses GSTP1 gene and lung cancer data from 44 studies." (PMID 37853012, 2023). "The measurement of STMN1 and GSTP1 proteins enabled the two main subtypes of lung cancer (non-small-cell and small-cell) to be distinguished with 57% specificity and 90% sensitivity." (PMID 36552956, 2022). "In this review, we discuss recent research advances on the role of ferroptosis and GSTP1 in lung cancer radiotherapy." (PMID 36589232, 2022). "Small RNA-mediated knockdown of GSTP1 in lung cancer cells showed increased activation of JNK and increased camptothecin-induced apoptosis." (PMID 33946704, 2021). "A lung cancer diagnostic panel consisting of APOA1, CO4A, CRP, GSTP1, and SAMP expression levels reached 95% sensitivity and 81% specificity." (PMID 31976313, 2020).
lung cancer (continued). "In addition, the GSTP1*CT genotype may be linked to the risk of lung cancer in Caucasians." (PMID 32183092, 2020). "In cases genotype frequency for GSTP1; AA (60%), AG (33.34 %), GG (6.67%) in which AG (Ile/Val, 41%) was lower in lung cancer cases comparatively to controls." (PMID 31554367, 2019). "Collectively, our findings indicate DUOX1 deficiency in lung cancers promotes dysregulated EGFR signaling and enhanced GSTP1-mediated turnover of EGFR cysteine oxidation, which result in enhanced nuclear EGFR localization and tumorigenic properties." (PMID 30890751, 2019). "GSTM1 (null)/GSTP1 (Ile/Ile) (OR=1.174, 95%CI=0.704-1.957), GSTT1 (null)/GSTP1 (Ile/Val+Val/Val) (OR=1.354, 95%CI=0.778-2.356) correlated to lung cancer risk and statistically non- significant." (PMID 31554367, 2019). "The genotype AG (Ile/Val) of GSTP1 found to be lower in smokers of lung cancer cases (33.03%) than controls (57.69%)." (PMID 31554367, 2019). "GSTP1-1 is overexpressed in various cancers, including gastric cancer, lung cancer, ovarian cancer, and precancerous lesions." (PMID 28747791, 2017). "CYP1A1, GSTM1, GSTP1 and GSTT1 polymorphisms and their association to lung cancer in a cohort of North Indian population was reported." (PMID 27090234, 2016). "We evaluated the main effects of phase I/phase II xenobiotic metabolism genes (CYP1A1, GSTM1, GSTP1 and GSTT1) in relation to lung cancer susceptibility using univariate as well as multivariate statistics." (PMID 23013535, 2012). "Our findings indicate GSTP1 to be a potential therapeutic target of lung cancer." (PMID 36709476, 2023). "Apart from the extensive research on the role of polymorphic GSTP1 expression in various cancers, including lung cancers, several studies have also examined the association of these polymorphic variants with susceptibility or outcome in a range of communicable and non-communicable lung diseases." (PMID 34988113, 2021). "Although early research suggested a weak association exists between certain GST gene mutations (e.g., GSTM1, GSTM3, GSTP1, and GSTT1) and risk of lung cancer, more recent work has not evidenced any definitive links between GSTM3 polymorphisms and lung cancer risk." (PMID 33568630, 2021). "But there are also reports the GSTM1 genotype both alone and in combination with the GSTP1 genotype alters the risk of developing lung cancer among nonsmokers." (PMID 32030321, 2020). "Interestingly, both NQO1 and GSTP1 expression levels were higher in colon and lung cancers as well as compared to the normal tissues, which was also reported in a previous study, though no significant influence on stomach cancer was found." (PMID 33087132, 2020). "Even though a growing number of studies have demonstrated that Gstp1 plays a key role in the development and maintenance of malignancy in several tumor types, mechanistic understanding of Gstp1 in mediating chemoresistance in lung cancer is sketchy." (PMID 31263672, 2019). "This group did not provide evidence for a strong association between GSTP1 rs1138272 and lung cancer susceptibility." (PMID 30740061, 2018). "GSTA1 was not detectable in lung tissue, however, GSTP1 increased significantly in lung tumors, indicating that GSTP1 may play a role in detoxification and maintenance of lung cancer cells." (PMID 26569310, 2015). "The results of the analysis of gene-gene interactions of CYP1A1 MspI T6235C, GSTM1 present/null, GSTT1 present/null and GSTP1 Ile105Val polymorphisms in lung cancer risk indicate that these genes do not interact in lung cancer development." (PMID 23013535, 2012). "Among non-smokers CYP1A1*2A and GSTP1 Ile105Val were the most important polymorphisms identified for lung cancer development." (PMID 22206016, 2011). "Therefore, we speculate that lung cancer cells might form a GSTP1-Keap1-Nrf2 positive feedback loop under ionizing radiation or oxidative stress, and play an anti-oxidative damage effect." (PMID 36589232, 2022).
lung cancer (continued). "The potential mechanism of targeting GSTP1 to inhibit tumor cells from evading ferroptosis leading to radioresistance has been proposed in this review, which implies that GSTP1 may play a key role in radiosensitization of lung cancer via ferroptosis pathway." (PMID 36589232, 2022). "Lung cancer is the most morbid and mortal disease among tumors, recent studies demonstrated that only GSTP1 Ala114Val polymorphism, but not GSTP1 Ile105Val polymorphism or wild-type genotype, was associated with improved survival in non-small cell lung cancer patients." (PMID 31357662, 2019). "The GSTP1 rs1138272 polymorphism may be related to the risk of non-small cell lung cancer in the Norwegian population and lung cancer in the Caucasian population of the United States." (PMID 30740061, 2018). "For example, GSTP1, a GST isoenzyme commonly overexpressed in breast, colon, and lung cancers, can be selectively inhibited by chalcones and flavonoids." (PMID 40806333, 2025). "Notably, GSTP1 has been shown to be involved in tumor development through the ferroptosis pathway and was suggested to be a novel negative regulator of ferroptosis that may play an important role in lung cancer radiotherapy by inhibiting ferroptosis." (PMID 38982523, 2024). "The combination of ezatiostat, a specific GSTP1 inhibitor, and crizotinib, an ALK inhibitor, can regulate the activity of lung cancer stem cells." (PMID 37941550, 2023). "Taken together, the bioinformatics analyses indicate that the findings we made using the mouse and human lung carcinoma CSC cellular models, regarding Gstp1 mediation of cisplatin resistance, are of clinical relevance and importance." (PMID 31263672, 2019). "In conclusion, GSTP1 may be a novel negative regulator of ferroptosis other than GPX4, may play an important role in lung cancer radiotherapy by inhibiting ferroptosis." (PMID 36589232, 2022). "From the tumors with highest incidence, we can stress the relevance of DNA methylation changes in the following genes found in LB: SHOX2 (for lung cancer); RASSF1A, RARB2, and GSTP1 (for lung, breast, genitourinary and colon cancers); and SEPT9 (for colon cancer)." (PMID 34208598, 2021). "Our subgroup analysis also found that some variants showed significant associations with lung cancer risk in smokers but not in non-smokers, for example CYP1A1 rs4646903 and GSTP1 rs1695." (PMID 28827732, 2017). "The most frequently analyzed genes like p16, DAPK, APC, RASSF1A, MGMT, FHIT, RARß and GSTP1 were applied as a means of detecting lung cancer or as prognostic factor but none of them had been used for therapy monitoring." (PMID 25675432, 2015). "In smokers, EPHX1 Tyr113His and SULT1A1 Arg213His polymorphisms reduced the risk of lung cancer, whereas CYP1A1*2A, CYP1A1*2C and GSTP1 Ile105Val imparted increased risk in non-smokers only." (PMID 22206016, 2011). "Previous research on the rs4891 locus of the GSTP1 gene is limited, with only a few studies analyzing its SNPs' association with Chronic Obstructive Pulmonary Disease (COPD) and lung cancer, Currently, there are no reports on its relationship with asthma onset." (PMID 40433469, 2025). "If GSTP1 could be shown to play a role in sustaining CSC phenotypes and the molecular pathways involved could be uncovered, it might serve as a useful therapeutic target for lung cancer." (PMID 36709476, 2023). "However, the expressions of pCaMK2A and GSTP1 were positively correlated in both clinical lung cancer samples and lung cancer cell lines, indicating CaMK2A/NRF2 S558 could regulate GSTP1 in a KEAP‐independent manner." (PMID 36709476, 2023). "The results revealed that Gstp1 expression was positively correlated with the MEK/ERK signaling pathway, which implied that Gstp1 may be affected by MEK/ERK signaling pathway in lung cancer." (PMID 31263672, 2019). "The low GSTP1 expression in the non-cancerous lung tissue and staging-wise elevation could be explored for lung cancer diagnosis and merits further investigation." (PMID 31263672, 2019).
lung cancer (continued). "MDR analysis identified two distinct predictor models for the risk of lung cancer in smokers (tobacco chewing, EPHX1 Tyr113His, and SULT1A1 Arg213His) and non-smokers (CYP1A1*2A, GSTP1 Ile105Val and SULT1A1 Arg213His) with testing balance accuracy (TBA) of 0.6436 and 0.6677 respectively." (PMID 22206016, 2011). "Few antimalarial drugs such as Quinine, Quinidine have been reported to exhibit inhibitory effect on GSTM1, GSTP1; however, none of them has been reported to inhibit GSTA1 specifically, which has been found overexpressed specially in lung cancer." (PMID 32405336, 2020). "In summary, we showed hypoxia‐induced CaMK2A activation leads to GSTP1 upregulation through direct NRF2 phosphorylation at S558, in turn eliminating ROS and facilitating homeostatic equilibrium through negative feedback, eventually contributing to lung cancer CSC maintenance." (PMID 36709476, 2023).